CRP (C-reactive protein)
Diseases named in the same sentence as CRP in open-access papers (continued):
Sharing a sentence is not in itself a finding about the gene and the disease.
infectious disease (continued). "Furthermore, using common inflammatory indicators, such as neutrophil count, procalcitonin (PCT), C-reactive protein (CRP), and ferritin may make it difficult to distinguish between infectious diseases (ID) and non-infectious inflammatory diseases (NIID)." (PMID 35967346, 2022). "The sensitivity and specificity of PCT for the differential diagnosis of infectious SIRS and non-infectious SIRS at this cut-off (91.5% and 93.7%, respectively) were significantly better than those of CRP and WBC." (PMID 25960877, 2014). "Although MBL is an acute phase reactant, it was not correlated with either inflammatory measures (CRP, PAI-1, fibrinogen, WBC count) or infectious disease exposure (Cp titers)." (PMID 19161617, 2009). "However, the C-reactive protein (CRP) value was approx. 0.4 mg/dL, and no infectious disease symptoms were observed." (PMID 28509122, 2017).
inflammation (259 papers, 2005 to 2026). Aberrant reaction of the microcirculation characterized by movement of fluid and leukocytes from the blood into extravascular tissues. "Higher DI‐GM scores were consistently linked with reduced systemic and intestinal inflammation, as evidenced by lower levels of CRP, TMAO, LPS, CEA, and calprotectin lower across quartiles." (PMID 41142011, 2025). "CRP has been linked to vascular inflammation and different CV disease manifestations such as MI for decades." (PMID 39842177, 2025). "Here the decreased lung washout of I-123 MIGB suggests that the sympathetic autonomic nerve dysfunction is linked to lung inflammation (serum measured IL-2 and C-reactive protein (CRP))." (PMID 41476959, 2025). "Signs of systemic inflammation in blood exams, such as neutrophilic leukocytosis associated with CRP increase, were found in 50% of our cohort." (PMID 40270003, 2025). "Chronic inflammation, reflected by elevated C-reactive protein (CRP), has been linked to the incidence, defibrillation success, recurrence, and prognosis of AF." (PMID 40034621, 2025). "The blood test indices including white blood cell counts, neurocyte counts, neutrophil-to-lymphocyte ratio, platelet count, C-reactive protein, and leucine-rich alpha 2-glycoprotein, which are associated with intestinal inflammation, significantly decreased." (PMID 39941545, 2025). "Second, besides the fact that CRP itself is an inflammatory indicator of UC, bilirubin has been considered a powerful antioxidant in oxidative stress/inflammation-associated disorders." (PMID 37817808, 2023). "CEA has been associated with several benign conditions, particularly chronic inflammation, and a previous study has investigated its association with widely accepted inflammatory markers, such as neutrophil/lymphocyte ratio, C-reactive protein, and IL-6." (PMID 36078939, 2022). "Childhood adversities and adulthood traumas were independently associated with an immune marker for chronic inflammation, C-reactive protein (CRP)." (PMID 35742178, 2022). "Chronic systemic inflammation signified by elevated C-reactive protein level is a key underlying pathophysiology in patients with T2D34." (PMID 36329257, 2022). "Consistent with our results regarding low PON1 activity in the high HDL-C/high CRP subgroup many other disease states associated with low-grade chronic inflammation also manifest low PON1 activity." (PMID 31480611, 2019). "A potential mechanism for these associations is suggested by the marginally significant (p = 0.059) finding of increased levels of CRP, a marker of systemic chronic inflammation, associated with RT." (PMID 30894578, 2019). "CRP is a hallmark of acute systemic inflammation and is a highly sensitive, yet unspecific, marker of inflammation." (PMID 28402963, 2017). "The acute peritoneal inflammation increases postoperative C-reactive protein concentrations (CRP) and causes postoperative pain." (PMID 29170623, 2017). "As a prominent marker of systemic chronic inflammation, CRP has been associated with poor muscle strength." (PMID 24000893, 2013). "CRP, a marker of chronic systemic inflammation negatively associated with physical activity, was significantly elevated in the skeletal muscle of the SO group relative to both the young and AO groups (297% and 82%, respectively; P<0.05)." (PMID 20520725, 2010). "There is also consistency between the SNPs we find associated with elevated CRP in chronic inflammation and those documented in basal CRP studies." (PMID 20877716, 2010). "When the CLR increases, it means that the relative amount of CRP to lymphocytes increases, which may further activate the NF - κB pathway, aggravate lung inflammation, and increase the risk of COPD." (PMID 40313545, 2025). "Studies have demonstrated that elevated levels of C-reactive protein (CRP) and interleukin-6 (IL-6) are associated with acute joint inflammation and may correlate with the severity of intra-articular soft tissue damage." (PMID 41007617, 2025).
inflammation (continued). "Modified LDLs have been found to cause vascular inflammation and thus increase serum CRP levels." (PMID 38792880, 2024). "This may be associated with chronic inflammation and a number of causative diseases linked to rising serum hs-CRP levels and chronic inflammation." (PMID 36136498, 2022). "However, the recently-developed high sensitivity assay (hs-CRP) can detect very low levels of CRP, and hence the presence of low-grade chronic inflammation such as vascular inflammation, a known cause of heart disease." (PMID 30934586, 2019). "Adopting salivary CRP for large‐scale screenings in childhood and adolescence could be an innovative public health strategy to identify individuals with inflammatory trajectories indicative of a heightened risk for inflammation‐related diseases." (PMID 40547317, 2025). "An inverse association between MD adherence and CRP suggests that following the MD might contribute to lower systemic inflammation levels, potentially reducing the risk of diseases associated with chronic inflammation." (PMID 38391824, 2024). "Therefore, the aim of the present study was to assess whether genotypes in the rs1205 SNP of the CRP gene influence the presence of low-grade chronic inflammation (hs-CRP ≥3 mg/l) considered a novel CV risk factor." (PMID 32514365, 2020). "Indeed, depletion of these antioxidants is often associated with chronic inflammation and other diseases and antioxidant therapy such as high-dose intravenous vitamin C treatment leads to decrease of inflammation markers such as CRP." (PMID 31298656, 2019). "It has been shown that higher levels of C-reactive protein are associated with a reduction in lung function, and a single high fat meal has been shown to significantly increase cholesterol and triglyceride levels as well as exhaled nitric oxide, a marker of airways inflammation." (PMID 24191194, 2013). "Chronic inflammation, marked by elevated cytokines like IL-6 and CRP, further suppresses albumin production and accelerates its breakdown." (PMID 40703630, 2025). "Inflammation was assessed in this study using CRP concentration ≥ 1 mg/dL as an indicator of mild or subclinical systemic inflammation." (PMID 41228397, 2025). "Inflammageing is defined as low‐grade chronic inflammation characterised by elevated circulating inflammatory proteins such as C Reactive Protein (CRP), which is observed during ageing." (PMID 41064932, 2025). "A systematic review of human clinical trials carried out between 1980 and 2019 revealed that curcumin supplementation increased IL-10 levels and decreased MCP-1, TNF-α, IL-6, and CRP levels, reflecting its anti-inflammatory properties in chronic inflammation." (PMID 40420174, 2025). "Previous studies have examined the relationship between neutrophil, lymphocyte and CRP levels and intra-amniotic inflammation (IAI)." (PMID 40579562, 2025). "Highly elevated expression of CRP in our data unequivocally confirms the close link between immunological senescence and chronic systemic inflammation." (PMID 40149697, 2025). "Local pulmonary inflammation induced by CS triggers a persistent, low-grade systemic inflammatory state, as evidenced by elevated white blood cell count, C-reactive protein (CRP), fibrinogen, and pro-inflammatory cytokines such as IL-1β and IL-6." (PMID 41516068, 2025). "Chronic inflammation, as reflected by elevated CRP levels, has been shown to impair lymphatic function by reducing lymphangion amplitude and frequency, leading to compromised lymphatic drainage and subsequent interstitial edema." (PMID 41011065, 2025). "Although the acute phase response (which lasts a few days) plays a positive role in the innate host defense mechanisms, increases in CRP have also been reported in chronic inflammation." (PMID 39086866, 2024).
inflammation (continued). "A study has proposed that pulmonary inflammation causes HAPE, and hypoxic stimulation causes the increase of tumor necrosis factor (TNF-α), interleukins (IL-1, IL-2, IL-6) and C-reactive protein (CRP) in blood." (PMID 37165489, 2024). "Our study found that in the univariate analysis between groups, the indicators related to myocardial inflammation and myocardial damage showed statistical differences, such as hs-CRP, CK-MB, LDH, LD1, α-HBD, AST, and ALT." (PMID 38228722, 2024). "It is important to note that CRP levels reflect an indirect measure of events in the synovium and that the total volume of synovial inflammation is what triggers the production of CRP." (PMID 38843126, 2024). "This longitudinal study examined associations between purpose in life and a marker of low-grade chronic inflammation (i.e., C-reactive protein [CRP]) in an age-heterogeneous sample of community-dwelling older adults." (PMID 37643057, 2024). "Pulmonary inflammation, in turn, leads to low-grade systemic inflammation involving acute-phase proteins such as C-reactive protein (CRP) and fibrinogen, as well as other cellular and soluble mediators." (PMID 39229275, 2024). "Beyond lung inflammation, mice exposed to CS have widespread inflammation throughout the body (elevated systemic CRP) and an imbalance between antioxidants and free radicals (i.e., oxidative stress)." (PMID 39061923, 2024). "Elevated erythrocyte sedimentation rate, C-reactive protein and other inflammatory markers are currently considered to be important indicators of active vascular inflammation." (PMID 38701260, 2024). "Several blood parameters, specifically blood serum IL-6, D-dimer, C-reactive protein, neutrophils, lymphocytes, monocytes, eosinophils, and basophils counts, were substantially higher than the normal ranges typical for acute viral inflammation." (PMID 37765004, 2023). "Hs-CRP is mainly used as a marker of subclinical chronic vascular inflammation and has a predictive value for future cardiovascular events." (PMID 36830878, 2023). "The sensitivity of FC is greater than that of CRP for detecting mild mucosal inflammation, while CRP appears to be a better biomarker of inflammation in patients with severe systemic inflammation." (PMID 36773075, 2023). "In our study, a preprocedural decline in the GNRI and an elevated CRP level, which reflect PEW and chronic inflammation status, are closely associated with poor AFS after lower-limb revascularization in chronic HD patients." (PMID 38202133, 2023). "In a sensitivity analysis, we repeated the computations after exclusion of patients with acute inflammation (CRP > 10.0 mg/L)." (PMID 36831896, 2023). "As a second assessment of pulmonary inflammation, levels of the inflammatory mediators CRP, KC, TNF-α, and VEGF-A were measured in BALF." (PMID 36466426, 2022). "CRP has been reported to have a significant prognostic value and a useful adjunctive test as well as being a marker of treatment response in inflammation disease." (PMID 35340256, 2022). "Some proteins such as C-reactive protein (CRP), serum amyloid A (SAA), procalcitonin (PCT), and interleukin-6 (IL-6) are considered to associate with the inflammation disease." (PMID 35198078, 2022). "Acute systemic inflammation, characterized by low albumin and high C-reactive protein (CRP) serum levels, is often observed in acutely ill hospitalized patients and can contribute to high levels of muscle wasting." (PMID 35235196, 2022). "In this vein, the results of our study showed that the participants suffered from systemic chronic inflammation, but that after the intervention with IH their CRP values significantly decreased compared to CG." (PMID 35564732, 2022). "A polymorphism (Tyr402His) in the CFH gene, which mainly controls the alternative complement activation, reduces the affinity for C-reactive protein (CRP), increasing the levels of unbound CRP in the choroid, leading to uncontrolled chronic inflammation." (PMID 36233311, 2022).
inflammation (continued). "Systemic inflammation is typically characterized by elevations in the levels of acute phase proteins, including C-reactive protein (CRP), apha-2 macroglobulin (a2M), haptoglobin (Hp) and serum amyloid P (SAP)." (PMID 34867953, 2021). "ROC analysis showed that both preoperative plasma ChE activity and CRP were good predictors of systemic inflammation in the early postoperative period, with a cut-off value in prediction of systemic inflammation of ≤4244 U L−1, and >54.2 mg L−1, respectively." (PMID 33935773, 2021). "CRP has been considered as an inflammatory mediator and induces renal inflammation via the CD32-NF-κB-dependent mechanism 6-8." (PMID 34671208, 2021). "Systemic inflammation (CRP = 60.8 ± 50.0 mg/L) was positively correlated with ADC values in the anterior corona radiata (p = 0.0089), genu of the corpus callosum (p = 0.0064) and external capsule (p = 0.0086) after adjusting for patients’ age." (PMID 34709472, 2021). "Systemic inflammation has been suggested as a possible link between chronic pruritic dermatoses and SD because an increased serum C-reactive protein level was documented in patients with SD." (PMID 34632036, 2021). "The majority of patients had higher ESR and/or CRP levels, consistent of active inflammation disease." (PMID 33560453, 2021). "ROC curves demonstrated only a moderate prognostic performance of CRP for prediction of myocardial inflammation with acceptable specificity and positive predictive values." (PMID 33542341, 2021). "Pulmonary inflammation was significantly affected by acute inflammation, as demonstrated by immune cell infiltration and NF-kB target gene (IL-6, CRP, COX-2, SOD1) upregulation." (PMID 34086835, 2021). "In contrast, disruption of Smad3 prevented CRP-exacerbated renal inflammation with sparse F4/80+ cell infiltration and attenuated IL-1β and MCP-1 upregulation as seen in CRP Tg/Smad3 KO mice." (PMID 34671208, 2021). "A positive correlation was observed between the urinary AGE fluorescence intensity and the CRP level, which is a marker of vascular inflammation." (PMID 31936498, 2020). "Previously, we found an association of increased progerin mRNA with overweight and chronic inflammation (hs-CRP)." (PMID 32872320, 2020). "Biomarkers for vascular inflammation include a high plasma level of C-reactive protein, soluble cell-adhesion molecules, von Willebrand factor, aldosterone, and proinflammatory cytokines like interleukin-6 or tumor necrosis factor α." (PMID 32408603, 2020). "Elevated serum C-reactive protein (CRP) level is widely used to indicate acute systemic inflammation in clinical practices." (PMID 32851079, 2020). "COPD is characterized by low-grade chronic systemic inflammation, and several biomarkers such as C-reactive protein (CRP), IL-6 and surfactant protein D (SPD) have been reported to be associated with increased risk of death in COPD patients." (PMID 29720140, 2018). "Particularly, chronic systemic inflammation in HD patients as indicated by increased levels of inflammatory markers such as C-reactive protein (CRP) and interleukin-6 (IL-6) are strong predictors for CVD and overall mortality." (PMID 29570616, 2018). "Erythrocyte sedimentation rate (ESR) and C-reactive protein (CRP) have been shown to be unreliable markers of disease activity, vascular inflammation, and progression." (PMID 30229280, 2018). "Our multivariate model indicated that CRP, a marker of chronic inflammation, and low adiponectin, a marker of adipose tissue dysfunction, were also independent determinants." (PMID 28594865, 2017). "In some inflammatory disorders, CRP is highly elevated, but in other disorders modest elevations of CRP have been found to be indicators of chronic inflammation with prognostic significance." (PMID 27352030, 2016). "CRP, TNF-α, and IL-6, which are a prominent markers of systemic chronic inflammation, have been significantly associated with poor HGS." (PMID 27078883, 2016).